SF3A3 (splicing factor 3a subunit 3)
Diseases named in the same sentence as SF3A3 in open-access papers:
SF3A3 is named in the same sentence as 26 diseases in open-access papers, as found by Europe PMC text mining. Sharing a sentence is not in itself a finding about the gene and the disease. The quoted sentences say what the papers report.
breast carcinoma (8 papers, 2022 to 2025). "Supplementary investigation of the molecular and cellular functions of these proteins identified PUF60 and SF3A3 as new spliceosome-related breast cancer RNA-binding proteins." (PMID 35453681, 2022). "Notably, SF3A3 has been shown to interact with MYC in breast cancer models, where translational modulation of SF3A3 induces metabolic reprogramming and acquisition of stem-like properties, ultimately potentiating MYC-driven oncogenesis in vivo." (PMID 40424306, 2025). "A previous study showed that SF3A3 facilitates breast cancer progression." (PMID 35248043, 2022). "SF3A3 selectively regulates MYC-driven splicing and metabolic reprogramming, which, in turn, induce tumorigenesis and breast cancer plasticity." (PMID 35248043, 2022). "In the SF3A/B sub-complex, SF3A3 expression was higher in MDA-MB-231 in agreement with recent observations stating that SF3A3 predicts molecular and phenotypic features of aggressive human breast cancers." (PMID 36725888, 2023). "Consequently, we identified five putative breast cancer RNA-binding proteins (PUF60, TFRC, KPNB1, NSF, and SF3A3) showing strong tumorigenic characteristics." (PMID 35453681, 2022). "Depletion of SF3A3 does not favor the survival of human primary fibroblasts, and results in lower proliferation of breast cancer cells." (PMID 35365208, 2022). "Thus, based on their tumorigenic characteristics presented in this study and their roles in other cancer types, we identified five new putative breast cancer RBPs: PUF60, TFRC, KPNB1, NSF, and SF3A3." (PMID 35453681, 2022).
non-small cell lung carcinoma (7 papers, 2019 to 2025). A group of at least three distinct histological types of lung cancer, including non-small cell squamous cell carcinoma, adenocarcinoma, and large cell carcinoma. "SF3A3 gene is a component of the spliceosome that represents a useful therapeutic target in non-small cell lung cancer, since its silencing is associated with induction of cell cycle arrest and cell death." (PMID 32664456, 2020).
bladder cancer (4 papers, 2022 to 2025). "Splicing factor 3A subunit 3 (SF3A3), which is encoded by SF3A3, is correlated with tumor stage and the prognosis of 49 patients with bladder cancer." (PMID 39132499, 2024). "Elevated expression of spliceosome components ensures precise pre-mRNA splicing, supporting cancer cell growth and survival.Previous study have shown that the upregulation of SF3A3 expression by its promoter hypomethylation, thereby mediating bladder cancer progression." (PMID 40424306, 2025). "However, the expression and function of SF3A3 in bladder cancer (BC) remains unclear." (PMID 35248043, 2022).
hepatocellular carcinoma (3 papers, 2021 to 2025). A malignant tumor that arises from hepatocytes. "SF3A3 encodes subunit 3 of the splicing factor 3a protein complex and act as a novel DNA repair-related prognostic signature in patients with hepatocellular carcinoma." (PMID 33516217, 2021).
glioma (2 papers, 2024 to 2025). A benign or malignant brain and spinal cord tumor that arises from glial cells (astrocytes, oligodendrocytes, ependymal cells). "Correlation analysis of SNRPD2 and SF3A3 expression against the expression of the 789 NJs across all glioma subtypes supported our hypothesis that decreased SNRPD2 and SF3A3 expression levels may contribute to greater NJ expression." (PMID 39972144, 2025).
liver cancer (2 papers, 2021 to 2022). An epithelial or non-epithelial malignant neoplasm that arises from the liver. "Previous studies reported that SF3A3 was upregulated and acted as an oncogenic protein in liver cancer." (PMID 35365208, 2022). "Moreover, among of them, RFC4, ZWINT, UPF3B, NCBP2, ADA, SF3A3 and GTF2H1 are independent prognostic indicators of liver cancer." (PMID 33516217, 2021).
lung cancer (2 papers, 2022 to 2025). A malignant neoplasm involving the lung. "We reported that SF3A3 was highly expressed and higher SF3A3 level was associated with a worse prognosis in lung cancer." (PMID 35365208, 2022). "We first determined the mRNA level of SF3A3 in lung cancer and found that SF3A3 was significantly upregulated in lung cancer compared to peritumor tissues." (PMID 35365208, 2022). "Consistently, the protein level of SF3A3 in lung cancer was also obviously elevated in lung cancer, as shown by IHC staining." (PMID 35365208, 2022). "Survival analysis revealed that high SF3A3 mRNA level predicted bad prognosis of lung cancer (log rank = 6.402, p = 0.0093)." (PMID 35365208, 2022).
endometrial cancer (1 paper, 2025). Primary or metastatic malignant neoplasm involving the endometrium (mucous membrane that lines the endometrial cavity). "Here, splicing factor 3A subunit 3 (SF3A3) is significantly upregulated in endometrial cancer (EC) tissues and associated with poor prognosis." (PMID 40598817, 2025). "The role of splicing factor 3A subunit 3 (SF3A3) in driving endometrial cancer (EC) progression and potential therapeutic interventions." (PMID 40598817, 2025). "SF3A3, a core component of the U2 small nuclear ribonucleoprotein (U2 snRNP), is upregulated in endometrial cancer (EC) and promotes tumor growth and cisplatin resistance." (PMID 40598817, 2025).
leukemia (1 paper, 2018). A malignant (clonal) hematologic disorder, involving hematopoietic stem cells and characterized by the presence of primitive or atypical myeloid or lymphoid cells in the bone marrow and the blood. "As expected, knockdown of MLL-interactors with known essential functions, such as RFC1, SF3A3, or CCT3, led to growth inhibition in both MLL-fusion cells and MLL-wild-type leukemia cells." (PMID 29777171, 2018).
lung squamous cell carcinoma (1 paper, 2025). "In lung squamous cell carcinoma, circTP63 competitively binds to miR-873-3p to upregulate FOXM1, promoting the proliferation of lung squamous cell carcinoma; circSCAP interacts with the SF3A3 protein to inhibit the malignant progression of non-small cell lung cancer." (PMID 40653497, 2025).
melanoma (1 paper, 2021). A malignant, usually aggressive tumor composed of atypical, neoplastic melanocytes. "Mutations in some of these genes of the splicing machinery, such as Serine and Arginine Rich Splicing Factor A3 and B3 (SF3A3, SF3B3), were significantly enriched in melanomas as compared to benign nevi." (PMID 34281234, 2021).
viral infection (1 paper, 2019). "For example, while U2 snRNP spliceosome components SF3A3 and SF3B are implicated in multiple RNA processes, these genes were also implicated in viral infection, translational processes, and DNA homologous recombination." (PMID 31386698, 2019).
tumor (10 papers, 2017 to 2025). "To confirm the tumor-promoting function of SF3A3 in NSCLC, we performed gain and loss of SF3A3 function in vitro." (PMID 35365208, 2022). "In addition, we performed IHC staining for Ki-67 and SF3A3 proteins in xenograft tumor tissue sections and found that the level of circSCAP was significantly inversely correlated to Ki-67 and SF3A3, but the level of SF3A3 was positively associated with Ki-67." (PMID 35365208, 2022). "Consistently, based on TCGA transcriptome data, we found that the expression of SF3A3 in CRC patients was significantly higher in tumor tissues than that in adjacent normal tissues (P < 0.05)." (PMID 40301637, 2025). "Summarily, our study revealed the complex network of HCC tumor microenvironment and its further clustering in terms of metabolic reprogramming, and identified SF3A3, a prognostic factor in HCC." (PMID 40424306, 2025). "Targeting SF3A3 with phenylethyl isothiocyanate (PEITC) effectively suppresses tumor progression, induces apoptosis, and reduces c‐FOS expression in vitro, in vivo, and patient‐derived tumor‐like cell clusters (PTCs)." (PMID 40598817, 2025). "The therapeutic potential of SF3A3 inhibition is further validated using patient‐derived tumor‐like cell clusters (PTCs), where PEITC and the c‐FOS inhibitor T‐5224 exhibit synergistic effects in suppressing EC." (PMID 40598817, 2025). "Together, these findings demonstrate that SF3A3 drives tumor progression in EC by promoting cell proliferation, enhanced cisplatin resistance, and reduced apoptosis in vitro and in vivo." (PMID 40598817, 2025). "Validation with our independent clinical samples dataset further confirmed that SF3A3 expression was significantly upregulated in EC tissues compared to tumor‐adjacent non‐cancerous endometrial tissues." (PMID 40598817, 2025). "Functionally, SF3A3 drives tumor progression by promoting cell proliferation, suppressing apoptosis, and enhancing cisplatin resistance in vitro and in vivo." (PMID 40598817, 2025). "We further validate PEITC as a potent SF3A3 inhibitor that effectively suppresses tumor progression and restores cisplatin sensitivity." (PMID 40598817, 2025). "To evaluate how SF3A3 interference affected the tumor-initiating ability of MHCC97-H cells, we conducted a colony formation assay." (PMID 40424306, 2025). "Recent studies have shown that the abnormal expression of SF3A3 is closely related to tumor progression." (PMID 35248043, 2022). "To explore the expression of SF3A3 in BC tissues, we first collected the clinical samples and confirmed tumor and normal tissues by using hematoxylin and eosin staining." (PMID 35248043, 2022). "Dataset analyses indicated that SF3A3 expression was significantly higher in LIHC tissues than in non-tumor tissues." (PMID 33344502, 2020). "Furthermore, we identify PEITC as a direct SF3A3 inhibitor, which effectively suppresses tumor growth and enhances cisplatin sensitivity." (PMID 40598817, 2025). "The TWAS results showed that high expression of one particular gene, SF3A3, which encodes an important splicing factor, was significantly associated with increased risk of CRC (P = 5.75 × 10−11), consistent with previous findings that indicated an oncogenic role for SF3A3 in tumor progression." (PMID 40301637, 2025). "SF3A3 has been previously identified as a potential driver of tumor progression." (PMID 40598817, 2025). "Consistent with the in vitro results, we found that SF3A3 supplementation successfully reversed the tumor-suppressing function of circSCAP overexpression, as displayed by the tumor volume and tumor weight alteration." (PMID 35365208, 2022).
tumor (continued). "Double immunofluorescence staining from the tumor tissue demonstrated that depletion of either SF3A3 or KDM5C showed significantly reduced fluorescence intensity compared to control cells while this decrease was enhanced by deletion of both SF3A3 and KDM5C, simultaneously." (PMID 35248043, 2022). "In addition, we detected the expression of SF3A3 in clinical samples and found that the expression of SF3A3 was increased in tumor tissue." (PMID 35248043, 2022). "To further investigate whether circSCAP exhibited tumor-suppressing function by downregulating SF3A3 in NSCLC, we carried out rescue assay in vitro and in vivo." (PMID 35365208, 2022). "Notably, SF3A3 expression varied slightly across tumor stages." (PMID 40598817, 2025). "Additionally, we demonstrated that SF3A3 overexpression obviously facilitated tumor growth in vivo." (PMID 35365208, 2022). "The anti‐tumor activity of PEITC was evaluated in normal endometrial cells and EC cell lines, revealing that cells with high SF3A3 expression (KLE and Ishikawa) were more sensitive to PEITC, as indicated by lower IC50 values." (PMID 40598817, 2025). "Analysis of cell proliferation in vitro and EC growth in vivo strongly indicated that SF3A3 and c‐FOS have tumor‐suppressive effects." (PMID 40598817, 2025). "Our study fills this important gap by identifying SF3A3 as a novel oncogenic regulator in EC, functioning through direct regulation of c‐FOS alternative splicing, which promotes tumor proliferation and chemoresistance." (PMID 40598817, 2025). "Overexpression of SF3A3 significantly increased tumor volume and weight after 35 days, without affecting the mice's body weight." (PMID 40598817, 2025). "All these findings suggested that knockdown of SF3A3 could induce CRC cell apoptosis, thus suppressing tumor growth." (PMID 40301637, 2025). "In this study, we found circSCAP could promote the degradation of SF3A3 in NSCLC cells and whether circSCAP exerted tumor-suppressing function through downregulating SF3A3 needed to be investigated." (PMID 35365208, 2022). "Mechanistically, SF3A3 regulates apoptosis and contributes to drug resistance, at least partially by modulating the AS of fos proto‐oncogene, AP‐1 transcription factor subunit (c‐FOS), a proto‐oncogene involved in cellular proliferation, drug resistance, and tumor growth." (PMID 40598817, 2025). "On the other hand, SF3A3 was downregulated in SNSCC, suggesting that its role may be cancer-type-specific or influenced by post-translational modifications, possibly reflecting distinct molecular pathways involved in different tumor types." (PMID 39765756, 2024). "Furthermore, the clinicopathological factors of SF3A3 expression level were positively correlated with tumor size but did not correlate with other such as age, gender, and tumor grade." (PMID 35248043, 2022). "Therefore, we analyzed SF3A3 expression in LIHC tissues and non-tumor tissues: SF3A3 expression in LIHC tissues was significantly higher than that in non-tumor tissues." (PMID 33344502, 2020).
cancer (9 papers, 2020 to 2025). A tumor composed of atypical neoplastic, often pleomorphic cells that invade other tissues. "This implies that knockdown of SF3A3 effectively reduces the cancer cells’ capacity to initiate tumors." (PMID 40424306, 2025). "Mechanistically, SF3A3 promotes the alternative splicing of c‐FOS, a proto‐oncogene implicated in cancer progression, leading to increased full‐length c‐FOS expression and upregulation of the anti‐apoptotic Bcl2/Bax ratio." (PMID 40598817, 2025). "Further CCK8 experiments identified that the anti-cancer drug efficacy of PEITC in CRC cells was significantly improved after SF3A3 overexpression (P < 0.05)." (PMID 40301637, 2025). "Most existing studies on SF3A3 have focused on its aberrant expression across various cancer types, but its functional role and mechanistic contributions to tumorigenesis—particularly in EC—have not been previously characterized." (PMID 40598817, 2025). "Abnormal expression of splicing factor 3A subunit 3 (SF3A3), a component of the spliceosome, has been confirmed to be related to the occurrence and development of various cancers." (PMID 35248043, 2022). "These putative BC progressor RBPs (PUF60, TFRC, KPNB1, NSF, and SF3A3) were integrated into a disease gene network to shed light on their molecular and cellular functions in cancer." (PMID 35453681, 2022). "To better understand the cellular functions of these prioritized RBPs (TFRC, KPNB1, PUF60, NSF, and SF3A3) in cancer, we next interrogated the HumanNet v2." (PMID 35453681, 2022). "As a splicing factor, SF3A3 may influence cancer progression through alternative splicing (AS) regulation." (PMID 40598817, 2025). "Notably, recent studies have begun to reveal broader oncogenic functions of SF3A3 in other cancers." (PMID 40598817, 2025). "In addition, PEITC targeting SF3A3 could be considered as a promising anti-cancer drug for CRC treatment, providing important insight into clinical application of our research findings." (PMID 40301637, 2025). "These included multitrait colocalization at 6 loci with a consistent direction of effect between CAD and cancer (ABO, PGAP3, ANGPTL4, SREBF1, HAUS6, and SYNJ2BP) and 7 with an opposing direction (CDKN1A, RGS19, CALCRL, SF3A3, LAMC1, MYO9B, and MIA3)." (PMID 40874306, 2025). "To investigate whether PEITC plays an anti-cancer role in CRC and whether it exerts effect through inhibiting SF3A3, we performed in vitro drug sensitivity test." (PMID 40301637, 2025). "Interestingly, NSF and SF3A3 have never been studied in cancer." (PMID 35453681, 2022). "Hence, it has been shown that ZFP207 interacts with the splicing components U2AF65 and SF3a3, and transcriptomic analysis revealed splicing defects after depletion of ZFP207 in cancer cells, although such splicing events were not thoroughly characterized." (PMID 35037361, 2022). "Interestingly, NSF, SF3A3, PRPF3, and MAGOHB have never been studied in cancer." (PMID 35453681, 2022).
SF3A3 also shares sentences with these, for which no sentence is quoted: colorectal cancer (2 papers); prostate carcinoma (2); acute promyelocytic leukemia (1); colon cancer (1); Hyperglycemia (1); Intellectual disability (1); microcephaly (1); microtia (1); nematode infection (1); oral cancer (1); Pectus carinatum (1); type-2 diabetes (1).